PTCD1 (pentatricopeptide repeat domain 1)
Description:
Mitochondrial protein implicated in negative regulation of leucine tRNA levels, as well as negative regulation of mitochondria-encoded proteins and COX activity. Also affects the 3'-processing of mitochondrial tRNAs.
Synonyms: KIAA0632
Tractability: PROTAC: ubiquitination databases record sites on it; its protein half-life has been measured.
Gene: Protein-coding gene on chromosome 7 (99,416,739 to 99,466,163, reverse strand). Ensembl gene ENSG00000106246.
Subcellular location: Mitochondrion; Mitochondrion matrix
Subcellular location (Human Protein Atlas): Mitochondria
Gene Ontology:
Molecular function: protein binding; RNA binding; tRNA binding; rRNA binding
Biological process: tRNA 3'-end processing; mitochondrial RNA modification
Cellular component: mitochondrial matrix; mitochondrion
Genetic constraint (gnomAD): Loss-of-function variants: 51 observed, 58.37 expected, observed/expected ratio (o/e) 0.87, 90% interval 0.7 to 1.1. The upper end of that interval is the gene's LOEUF score, 1.1, which puts it in group 4 of 6, group 1 being the genes least tolerant of losing a copy. Missense variants: 918 observed, 938.44 expected, observed/expected ratio (o/e) 0.98, 90% interval 0.93 to 1.03. Synonymous variants: 413 observed, 409.67 expected, observed/expected ratio (o/e) 1.01, 90% interval 0.93 to 1.09.
Homologues: Orthologues: chimpanzee PTCD1 (98% identical), macaque PTCD1 (93% identical), dog PTCD1 (77% identical), pig PTCD1 (75% identical), guinea pig PTCD1 (74% identical), rabbit PTCD1 (74% identical), mouse Ptcd1 (73% identical), rat Ptcd1 (73% identical), tropical clawed frog ptcd1 (46% identical), zebrafish ptcd1 (44% identical). Paralogues in human: OGFOD2 (8% identical).
Diseases named in the same sentence as PTCD1 in open-access papers:
PTCD1 is named in the same sentence as 14 diseases in open-access papers, as found by Europe PMC text mining. Sharing a sentence is not in itself a finding about the gene and the disease. The quoted sentences say what the papers report.
Obesity (3 papers, 2020 to 2024). Accumulation of substantial excess body fat. "The ribosomal RNA maturation protein PTCD1 is essential for mitochondrial protein synthesis and its reduction causes adult-onset obesity and liver steatosis." (PMID 33024056, 2020). "Impaired mitochondrial gene expression due to the heterozygous knockout of PTCD1, a mitochondrial RNA processing enzyme, for example, has been linked to later-life obesity in mice." (PMID 32221480, 2020). "Recently we showed that reduced mitochondrial protein synthesis caused by haploinsufficiency of PTCD1 led to increased weight gain in haploinsufficient mice (Ptcd1+/-) on a NCD from 15 weeks of age compared to their wild type littermates (Ptcd1+/+), causing adult onset obesity by 30 weeks of age." (PMID 33024056, 2020). "For instance, the homozygous knockout of Ptcd1 is lethal during embryogenesis; however, heterozygous mice with diminished PTCD1 levels exhibit obesity during adulthood." (PMID 39201474, 2024). "Here we dissect the mechanisms that lead to adult-onset obesity by investigating how reduction in mitochondrial protein synthesis from early age in haploinsufficient Ptcd1 mice can affect metabolism and cell signaling on normal and high fat diets." (PMID 33024056, 2020). "Recently we identified that reduction in PTCD1, a protein required for mitochondrial protein synthesis, can lead to adult-onset obesity." (PMID 33024056, 2020). "Acetate levels were significantly increased in serum of HFD Ptcd1+/- mice but not in NCD-fed Ptcd1+/- mice compared to controls, consistent with the previously reported protective role of acetate in diet induced obesity and the HFD protective effects in Ptcd1+/- mice." (PMID 33024056, 2020).
asthma (1 paper, 2020). "Only 3 (PTCD1, CYC1 and MT-CO1) of the 48 significantly differentially expressed genes were more highly expressed in individuals with asthma; the other 45 had lower expression in individuals with asthma as compared with individuals without asthma." (PMID 33237978, 2020).
bladder cancer (1 paper, 2022). "Reasonably, downregulation of PTCD1 in bladder cancer likely causes the abnormal regulation of m6A-related regulators, where more studies need to be done to prove the hypothesis." (PMID 35799606, 2022). "The results revealed that PTCD1 expression in bladder cancer tissues gradually reduced with the growth of stage and grade." (PMID 35799606, 2022).
Bladder Urothelial Carcinoma (1 paper, 2022). "However, the effect and mechanism of PTCD1 in the development of bladder urothelial carcinoma (BLCA) remain unclear." (PMID 35799606, 2022).
cardiomyopathy (1 paper, 2024). A disease of the heart muscle or myocardium proper. "Cardiomyopathy is also a major pathogenic feature of heterozygous Ptcd1 knockout mice and is the cause of premature death in tissue-specific homozygous Ptcd1 knockout mice." (PMID 38779771, 2024). "PTCD1 was identified as an essential factor required for 16S rRNA stability and early ribosome assembly and mutations in PTCD1 have been linked to cardiomyopathy in patients." (PMID 38779771, 2024).
emphysema (1 paper, 2022). "Our results indicate an unchanged PTCD1 expression among nonsmokers, smokers, and emphysema patients." (PMID 35884802, 2022). "We did not detect any significant changes in PTCD1 and PTCD3 protein levels between controls and emphysema by Western blotting." (PMID 35884802, 2022).
Insulin resistance (1 paper, 2020). Increased resistance towards insulin, that is, diminished effectiveness of insulin in reducing blood glucose levels. "Reduced mTOR signaling in the liver of Ptcd1+/- mice may be a way to protect liver function against the development of insulin resistance and metabolic dysfunction early in life." (PMID 33024056, 2020).
Leigh syndrome (1 paper, 2024). A progressive neurological disease defined by specific neuropathological features associating brainstem and basal ganglia lesions. "Low ATP hits that increased cytosolic ROS without affecting mitochondrial ROS included PTCD1, a mitochondrial ribosomal assembly factor and AD-associated risk gene, and PTCD3, a related mitochondrial ribosomal protein in which mutations can cause Leigh syndrome." (PMID 38207075, 2024).
lymph node metastasis (1 paper, 2022). "Kaplan–Meier curves indicated that downregulation of PTCD1 led to poor prognosis of BLCA, which was reflected in the late clinical features of cancer pathological staging and lymph node metastasis." (PMID 35799606, 2022).
steatosis (1 paper, 2020). Increased lipid within the cytoplasm of cells. "The SAPK/JNK phosphorylation levels were also increased in the liver of Ptcd1+/- mice fed a HFD compared to controls, despite the decrease in liver steatosis but consistent with the increased transcriptional activation of Atf4, Atf5 and Chop." (PMID 33024056, 2020). "In contrast, we identified reduced lipid accumulation in the livers of high fat fed Ptcd1+/- mice, suggesting that, despite activation of the SAPK/JNK pathway, the liver can be protected from diet induced steatosis." (PMID 33024056, 2020). "In the livers of Ptcd1+/- mice fed a HFD the steatotic vesicles were smaller and formed clusters suggesting that reduced mitochondrial protein synthesis may protect the liver from steatosis on a HFD." (PMID 33024056, 2020).
tumor (3 papers, 2022 to 2024). "The estimation of associations between PTCD1 and tumor mutations, tumor immunities, and m6A methylations was performed." (PMID 35799606, 2022). "Mechanistically, PTCD1 played a regulatory role in BLCA progression through multiple tumor-related pathways containing PI3K-Akt signaling, ECM-receptor interaction, oxidative phosphorylation, and extracellular matrix organization." (PMID 35799606, 2022). "The Human Protein Atlas (HPA) database was used to explore the protein expression of PTCD1 in normal bladder and tumor tissues." (PMID 35799606, 2022). "Next, TCGA-BLCA cohorts were classified into low- or high-PTCD1 groups based on the best cut-off expression of PTCD1 (FPKM = 1.128054) in tumor samples as the threshold." (PMID 35799606, 2022). "PTCD1 may be involved in immune function and immune cell infiltration, and may play a role in tumor progression and metastasis." (PMID 37598251, 2023). "Further, our data suggested that PTCD1 may participate in the immunological functioning and immune cell infiltration and might play certain roles in tumor progression and metastasis, which could be acted as a potential prognostic target of BLCA." (PMID 35799606, 2022). "When analyzing the basic characteristics of patients, all patients in the low-expression group belong to high-grade tumors, which may indicate that PTCD1 expression is a factor in predicting tumor grade." (PMID 35799606, 2022). "Second, the absence of PTCD1 protein expression level in tumor specimens should be further detected." (PMID 35799606, 2022). "Combined with follow-up analyses, PTCD1 may influence cancer progression mainly by regulation of the immune microenvironment, but this might not enhance distant metastasis of tumor cells." (PMID 35799606, 2022).
cancer (1 paper, 2022). A tumor composed of atypical neoplastic, often pleomorphic cells that invade other tissues. "In the present work, PTCD1 expression level was highly impacted by the mutation rate of same cancer-related genes, which were of high mutation probability in BLCA." (PMID 35799606, 2022). "As above shown, PTCD1 is very likely involved in formation and development of cancer." (PMID 35799606, 2022).
PTCD1 also shares sentences with these, for which no sentence is quoted: diabetes (1 paper); Onset (1).